MSI2 (musashi RNA binding protein 2)
Diseases named in the same sentence as MSI2 in open-access papers (continued):
Sharing a sentence is not in itself a finding about the gene and the disease.
neurofibroma (3 papers, 2019 to 2020). An intraneural or extraneural neoplasm arising from nerve tissues and neural sheaths. "To this end, we first detected MSI2 expression in fresh tissue samples and found a significantly higher expression of MSI2 in MPNSTs than in neurofibromas." (PMID 31053152, 2019). "We first determined whether MSI2 expression was significantly higher in NF1-MPNSTs than it was in neurofibromas through analysis of two MPNST patient cohorts, Jessen_cohort (GEO: GSE41747) and Kolberg_cohort (GEO: GSE66743)." (PMID 32606289, 2020). "According to our study, MSI2 is highly expressed in NF1 MPNSTs relative to that in neurofibromas." (PMID 31053152, 2019). "Our previous study found that knockdown of HMGA2 inhibits NF1-MPNST growth through MSI2 and that MSI2 expression in NF1-MPNSTs is higher than that in neurofibromas." (PMID 32606289, 2020).
pancreatic ductal adenocarcinoma (3 papers, 2020 to 2022). An infiltrating adenocarcinoma that arises from the epithelial cells of the pancreas. "In pancreatic ductal adenocarcinoma, recent study has revealed that MSI2-mediated tumorigenesis was associated with Hippo pathway." (PMID 35102250, 2022). "It has been reported that Krüppel-like factor 4 (KLF4) transcriptionally inhibits MSI2 expression by directly binding to the MSI2 promoter in multiple pancreatic ductal adenocarcinoma (PDAC) cell lines." (PMID 33553241, 2020).
SARS-CoV infection (3 papers, 2020 to 2023). "MSI2 is a member of the Musashi protein family, which is reported to be downregulated in the SARS-CoV infection." (PMID 37314180, 2023). "On the other hand, the coding gene for Musashi-2 (MSI2) RNA-binding protein was downregulated in SARS-CoV infection." (PMID 32754004, 2020).
triple-negative breast carcinoma (3 papers, 2020 to 2025). An invasive breast carcinoma which is negative for expression of estrogen receptor (ER), progesterone receptor (PR), and human epidermal growth factor receptor 2 (HER2). "At this time, very limited data is available on different MSI2 transcript variants, though a study in triple-negative breast cancer suggests possible isoform-specific roles." (PMID 40843174, 2025). "Another recently has highlighted differential expression patterns of Msi-2 isoforms in triple-negative breast cancer (TNBC) and has demonstrated that downregulation of a predominant isoform (Msi-2a) is associated with TNBC progression." (PMID 36371343, 2022). "This study investigated the expression and phenotypic functions of two major alternatively spliced MSI2 isoforms (MSI2a and MSI2b) and the potential molecular mechanisms involved in triple-negative breast cancer (TNBC) progression." (PMID 32448269, 2020).
Brain Tumor (2 papers, 2013 to 2016). "Currently, it is unclear why the knockdown of MSI2 reduces the growth of brain tumor cells." (PMID 23667531, 2013). "Thus, further study will be needed to define the roles of MSI2 in brain tumor cells." (PMID 23667531, 2013). "Therefore, we expanded our analysis of SOX2-associated proteins by determining whether decreasing MSI2 and USP9X expression influences the behavior of brain tumor cells." (PMID 23667531, 2013). "Recent studies have implicated MSI2, a putative RNA binding protein, and USP9X, a deubiquitinating enzyme, in several cancers, but not brain tumors." (PMID 23667531, 2013). "Furthermore, MSI2 and USP9X have been implicated in other cancers, but their roles in brain tumors have not been examined." (PMID 23667531, 2013).
esophageal squamous cell carcinoma (2 papers, 2020 to 2024). Esophageal squamous cell carcinoma (ESCC) is a type of esophageal carcinoma (EC) that can affect any part of the esophagus, but is usually located in the upper or middle third. "MSI2 silencing impairs cell proliferation and EMT in esophageal squamous cell carcinoma." (PMID 31952541, 2020).
mesothelioma (2 papers, 2021 to 2022). A usually malignant and aggressive neoplasm of the mesothelium which is often associated with exposure to asbestos. "The silencing of MSI2 in mesothelioma or overexpression of Adar2 in mesothelial cells resulted in increased RBM8A protein levels." (PMID 34944051, 2021). "We determined that MSI2 is more abundantly expressed compared to MSI1 in mesothelioma and mesothelial cells." (PMID 34944051, 2021). "Therefore, we put forward the hypothesis that RNA editing and MSI2 are likely to have a broad implication in the mesothelioma phenotype." (PMID 34944051, 2021).
osteoporosis (2 papers, 2022 to 2025). A condition of reduced bone mass, with decreased cortical thickness and a decrease in the number and size of the trabeculae of cancellous bone (but normal chemical composition), resulting in increased fracture incidence. "In our study, it was confirmed that Msi2 greatly reduced both RNA and protein levels in aging mouse bone samples, and theMsi2-deficient mice showed an age-dependent osteoporosis-like phenotype." (PMID 35301280, 2022). "The depletion of Msi2 in mice led to decreased bone mass with increased marrow adipocytes, resembling aging-induced osteoporosis." (PMID 35301280, 2022). "Our research established a link between osteoporosis and RNA-binding proteins, and we discovered a regulatory relationship between MSI2 and PPARγ signaling." (PMID 35301280, 2022). "Exploring compounds and small molecules that regulate Msi2 will promote the treatment of cancer and osteoporosis." (PMID 35301280, 2022). "Here, we revealed the functions of Msi2 in balancing the osteoblast/adipocyte lineage commitment of BMSCs and aging-induced osteoporosis." (PMID 35301280, 2022). "Our results revealed that Msi2 is an important contributor to osteoporosis by modulating protein translation." (PMID 35301280, 2022). "Msi2 knockout mice displayed accumulation of adipocytes in the bone marrow cavity and decreased bone mass, mimicking osteoporosis." (PMID 35301280, 2022). "Msi2 knockout mice exhibited decreased bone mass with substantial accumulation of marrow adipocytes, similar to aging-induced osteoporosis." (PMID 35301280, 2022). "The decreased expression of Msi2 in BMSCs of aged mice suggests that the reduced expression of Msi2 during ageing shifts the balance of osteogenesis/adipogenesis towards adipogenesis, leading to osteoporosis." (PMID 40681473, 2025). "The link between the RNA-binding protein Msi2 and osteoporosis is worth exploring in depth." (PMID 35301280, 2022). "Furthermore, we found that Msi2 expression was decreased in aged BMSCs, indicating that the decreased Msi2 expression during aging shifts the osteogenesis/adipogenesis balance toward adipogenesis and leads to osteoporosis." (PMID 35301280, 2022). "Furthermore, the expression of Msi2 decreased significantly during the aging process of mice, indicating that decreased Msi2 function during aging contributes to abnormal accumulation of adipocytes in bone marrow and osteoporosis." (PMID 35301280, 2022). "Similar to the phenotype of the Msi2 knockout mice, abnormal accumulation of adipocytes in the bone marrow cavity of the aged mice was observed, suggesting the occurrence of aging-related osteoporosis." (PMID 35301280, 2022). "Thus, our results provide a putative biochemical mechanism for aging-related osteoporosis, suggesting that modulating Msi2 function may benefit the treatment of bone aging." (PMID 35301280, 2022). "In aged BMSCs, the Msi2 expression level decreased, and the balance of BMSC differentiation shifted toward adipogenesis, which led to osteoporosis indicated by abnormal accumulation of adipocytes in the bone marrow cavity and decreased bone mass." (PMID 35301280, 2022). "This work defined the role of Msi2 in regulating MSC commitment and identified a new target for aging-induced osteoporosis treatment." (PMID 35301280, 2022).
attention deficit-hyperactivity disorder (1 paper, 2023). A disorder characterized by a marked pattern of inattention and/or hyperactivity-impulsivity that is inconsistent with developmental level and clearly interferes with functioning in at least two settings (e.g. at home and at school). "Results of a linkage analysis suggested relationships between SRD and SNPs within the MSI2 gene and upstream of the attention-deficit/hyperactivity disorder (ADHD)-related LPHN3 gene." (PMID 36675818, 2023).
B-cell lymphoma (1 paper, 2021). "Specifically, downregulation of MSI2 in primary CLL cells and in three B-cell lines (MEC1, CRL-2261, and Ramos) reduced cell viability, suggesting MSI2 plays a role in CLL-cell and B-cell lymphoma-cell survival." (PMID 33504942, 2021).
brain cancer (1 paper, 2013). A primary or metastatic malignant neoplasm affecting the brain. "To begin to understand the roles of SOX2-associated proteins in brain cancer, we focused on two SOX2-associated proteins, Musashi 2 (MSI2) and Ubiquitin Specific Protease 9x (USP9X)." (PMID 23667531, 2013).
colorectal polyps (1 paper, 2021). "Based on analysis of H-score, there was a significant increase in MSI2 protein expression in colorectal polyps (all tubulovillous adenoma by histology) versus normal mucosa (median values, 140 versus 60; average values, 138.75 versus 60.25; p<0.001)." (PMID 34237057, 2021).
degenerative arthritis (1 paper, 2021). "Additionally we determined the effect of MSI2 inhibitor on HSCs and progenitors from CLL patients and from age-matched people undergoing hip replacement for degenerative arthritis." (PMID 33504942, 2021).
endometriosis (1 paper, 2022). The growth of functional endometrial tissue in anatomic sites outside the uterine body. "As these data suggest a potential mechanistic involvement of Musashi proteins in endometriosis, the aim of this study is to elucidate the effect of MSI-1 and MSI-2 knockdown on endometriosis development in vitro." (PMID 35269992, 2022). "Specifically, the expression of MSI-1, MSI-2, of the transcription factor HES-2 and the cell cycle regulator p21 are significantly reduced in patients with endometriosis according to the data." (PMID 35269992, 2022).
head and neck squamous cell carcinoma (1 paper, 2017). A squamous cell carcinoma that arises from any of the following anatomic sites: lip and oral cavity, nasal cavity, paranasal sinuses, pharynx, larynx, and salivary glands. "In 2 cancer types, head and neck squamous cell carcinoma and uterine corpus endometrial carcinoma, a 2–3 fold increase in Msi2 variant 2 transcript levels occurred without a significant increase in the canonical Msi2 transcript." (PMID 28912529, 2017).
hepatitis C (1 paper, 2025). "Finally, MSI2, identified in the hepatitis C pathways, was proposed for the hallmarks of “Metabolic Reprogramming”, suggesting that these genes could be modulating the use of energy resources." (PMID 40136626, 2025).
Hyperglycemia (1 paper, 2017). An increased concentration of glucose in the blood. "Differential methylation of the MSI2 gene (chr17:55484635) in blood and islet cells is strongly related to hyperglycemia." (PMID 28542303, 2017). "Our findings suggest that epigenetic perturbation on the target site (chr17:55484635) of MSI2 gene in circulating blood and pancreatic islets should represent or affect hyperglycemia." (PMID 28542303, 2017).
Impaired glucose tolerance (1 paper, 2018). An abnormal resistance to glucose, i.e., a reduction in the ability to maintain glucose levels in the blood stream within normal limits following oral or intravenous administration of glucose. "They identified hypomethylation of two genes, Musashi RNA-Binding Protein 2 (MSI2) and CXXC-Type Zinc Finger Protein 4 (CXXC4), in individuals with T2D and impaired glucose tolerance, compared to healthy controls." (PMID 30564199, 2018).
insulinoma (1 paper, 2020). "MSI2 overexpression blocked MIN6 cell (a mouse insulinoma cell line) proliferation, whereas MSI2 knockdown augmented MIN6 cell proliferation." (PMID 32448269, 2020).
kidney tumors (1 paper, 2014). "Furthermore, thesystematic downregulation of Msi1/Msi2 and high frequency ofMsi1 mutations in kidney tumors suggests that kidney would be aninformative model for studying Msi loss-of-function and its consequences in cancer." (PMID 25380226, 2014).
male infertility (1 paper, 2024). The inability of the male to effect fertilization of an ovum after a specified period of unprotected intercourse. "Two transgenic mouse models with germ cell-specific overexpression of MSI1 or MSI2 transcripts showed a significant decrease in the ability of sperm to bind effectively to the zona pellucida of a control mouse oocyte, with MSI2 overexpression resulting in male infertility." (PMID 39285325, 2024).
malignant glioma (1 paper, 2024). A grade III or grade IV glioma arising from the central nervous system. "MSI1, a homologous protein of MSI2, has been reported to regulate radiation‐induced DNA damage by promoting non‐homologous end joining in malignant gliomas, and inhibition of MSI1 increases radiosensitivity of malignant gliomas." (PMID 38645664, 2024).
melanoma (1 paper, 2020). A malignant, usually aggressive tumor composed of atypical, neoplastic melanocytes. "MS analysis of RNF157 interacting proteins in melanoma cells revealed its interaction with RNA binding protein MSI2 (Musashi RNA-binding protein 2), which is involved in cell cycle regulation and proliferation of cancer stem cells (CSCs)." (PMID 33171937, 2020).
metastatic disease (1 paper, 2025). "Collectively, these results highlight that MSI2 might be a potential therapeutic target for TNBC treatment and could serve as a prognostic biomarker for patients with metastatic disease." (PMID 39990676, 2025).
muscular atrophy (1 paper, 2024). The loss of muscle tissue due to inactivity or disease. "Loss of Msi2 results in muscular atrophy and fiber-type switching to type I fibers." (PMID 38373797, 2024).
myotonic dystrophy type 1 (1 paper, 2024). Steinert disease, also known as myotonic dystrophy type 1, is a muscle disease characterized by myotonia and by multiorgan damage that combines various degrees of muscle weakness, arrhythmia and/or cardiac conduction disorders, cataract, endocrine damage, sleep disorders and baldness. "We recently reported that upregulation of Musashi 2 (MSI2) protein in the rare neuromuscular disease myotonic dystrophy type 1 contributes to the hyperactivation of the muscle catabolic processes autophagy and UPS through a reduction in miR-7 levels." (PMID 38760841, 2024).
oral cancer (1 paper, 2019). "The MSI2 mRNA expression in oral cancer is higher in males and it is correlated with tumor grade." (PMID 31878037, 2019). "In addition to these results, some information regarding the potential biological functions of MSI2 in oral cancer emerged from the evaluation of the TMAs." (PMID 31878037, 2019).
pancreatic adenocarcinoma (1 paper, 2019). "Previous reports have shown that MSI2 regulates the 3’UTR of HMGA2 in pancreatic adenocarcinoma, but based on our results from luciferase reporter assays, the MSI2 promoter region is directly bound by HMGA2, and knockdown or overexpression of MSI2 expression did not affect HMGA2 expression." (PMID 31053152, 2019).
prostate carcinoma (1 paper, 2024). A carcinoma that arises from epithelial cells of the prostate gland. "In prostate cancer, MSI2 can bind to the 3’-UTR region of androgen receptor (AR) mRNA, enhancing its mRNA stability and translation activity, and regulating the PI3K/AKT/mTOR pathway." (PMID 39097735, 2024).
pulmonary fibrosis (1 paper, 2025). Chronic progressive interstitial lung disorder characterized by the replacement of the lung tissue by connective tissue, leading to progressive dyspnea, respiratory failure, or right heart failure. "Additionally, ionizing radiation markedly elevates the RNA-binding protein MSI2 in AT2 cells, triggering ZEB1-driven EMT, collagen deposition and radiation-induced pulmonary fibrosis." (PMID 40988754, 2025).
retinoblastoma (1 paper, 2013). A malignant tumor that originates in the nuclear layer of the retina. "Within the recurrent focal gains or losses in the RbTKO retinoblastoma model, we found 12 in cancer genes, including Lmo1 in 5/6 samples; Ndrg1, Brd4, Fbxo11, and Rbm15 in 4/6 samples; Mdm4, Msi2, and Ezh2 in 3/6 samples." (PMID 23765217, 2013).
virus infection (1 paper, 2023). "Inhibition of MSI2-RNA binding reduced HCV IRES activity, viral replication and liver hyperplasia in humanized mice predisposed by virus infection and alcohol high-cholesterol high-fat diet." (PMID 37117191, 2023).